AFP (alpha fetoprotein)
Diseases named in the same sentence as AFP in open-access papers (continued):
Sharing a sentence is not in itself a finding about the gene and the disease.
cancer (continued). "The cancer cells were also positive for cytokeratin-7 (CK7), CK19, and CA19-9 but negative for CK20, alpha-fetoprotein (AFP), and carcinoembryonic antigen (CEA)." (PMID 38185762, 2024). "Generally, the immune response to pure AFP is poor (CD8+ lymph stimulation is observed, but no anti-cancer response) and requires additional stimulation, such as a combination of AFP with daunorubicin." (PMID 36768863, 2023). "The AYA group had a higher AFP level and a higher prevalence of family history of HCC or other cancers than the non-AYA group (P < 0.01 and P < 0.05)." (PMID 35729607, 2022). "DM patients with malignancy showed a significantly higher proportion of abnormal AFP and ANA results than patients without malignancy (p = 0.02 and p = 0.01, respectively) based on chi-squared tests." (PMID 33633147, 2021). "Accurate detection of AFP-negative and small HCC tumors can lead to early diagnosis, treatment, and reduced cancer-related mortality." (PMID 27390551, 2016). "In CLC, AFP was positive/negative (1/2), whereas vitamin K absence-II (PIVKA-II) and CEA (carcinoembryonic antigen) were negative, and CA19-9 (carcinoma 19-9) was positive/negative (1/2)." (PMID 23192764, 2013). "One of promising marker is Cancer-Testis Antigens, but more studies need to be done to select one or more CTA combined (or not) with the detection of the AFP mRNA expression." (PMID 22690340, 2012). "Due to the low nanogram levels (6 ng/mL) present in circulating adult HAFP, transformed AFP and its exposed GIP segments are not available to adult humans to aid in bodily defense from cancer and benign growths." (PMID 24212829, 2011). "On the other hand, AFP (2.1 vs. 2.44), ALP (65 vs. 77), CA125 (22.66 vs. 241.5), CEA (1.27 vs. 1.41), HE4 (43.77 vs. 140.9), PCT (0.23 vs. 0.26), and PLT (223.5 vs. 265) values were significantly lower in cancer patients compared to non-cancer patients." (PMID 40943960, 2025). "Additionally, cancer markers, carcinoembryonic antigen (CEA) and alpha-fetoprotein (AFP), were negative." (PMID 40747175, 2025). "Furthermore, patients developing HCC had higher AFP levels and APRI scores compared to those who did not develop cancer." (PMID 39064561, 2024). "However, with normal AFP levels and the scans showing gradual enhancement—features not aligning with HCC —the possibility of other malignant tumors necessitates consideration." (PMID 39640280, 2024). "AFP has been classified as an HCC marker due to its usefulness in HCC prognosis and diagnosis without biopsy intervention; nonetheless, due to the heterogeneity of this type of cancer, not all HCC tumors are AFP positive." (PMID 37176094, 2023). "Importantly, the reproducibility and precision with a relative standard deviation of <15% and specificity with no response to other cancer biomarkers such as CA125, PSA, and hCG, etc., were satisfactory for AFP detection in HCC patients." (PMID 34557478, 2021). "The high sensitivity and specificity of the combination of three circRNAs and AFP could be used to distinguish HBV-infected patients with and without cancer." (PMID 34660653, 2021). "The carcinoma markers CEA, CA19–9, and AFP are not specific for PHNECs." (PMID 28683830, 2017). "One limitation of the current strategy is that it may be effective only for AFP-positive HCC treatment, and it is not clear if the cancer cells will develop resistance to the treatment by unknown mechanisms." (PMID 25691059, 2015). "Furthermore, when hepatocellular carcinogenesis prediction was performed using age, Alanine Aminotransferase (ALT) value, and alpha fetoprotein (αFP) value, the cases with subjects 65 years or younger, and ALT<30, αFP <5 are predicted to not develop cancer after 5 years of follow‐up." (PMID 38146079, 2023).
cancer (continued). "To this end, we examined the serum AFP values and ultrasonic results obtained at the time of HCC detection in a hospital-based cohort of patients undergoing regular surveillance in the absence of cancer-related symptoms, and then assessed survival outcomes according to diagnostic status." (PMID 32845895, 2020). "However, both large and small carcinoma cells were totally c-Kit-negative, CD34-negative, αSMA-partially positive, PLAP-positive, SALL4-focally positive, AFP-negative, CD30-negative, glypican-3-slightly positive and Oct3/4-negative using immunohistochemical staining." (PMID 32990826, 2020). "Notably, these cancer biomarkers functionally comprised of several cytokines (IL-6, MIF, TGF-α, TNFα), apoptosis-related proteins (sFas, sFasL, TRAIL), growth and angiogenic factors (FGF2, HGF, SCF, VEGF), hormones (leptin, prolactin) and other biomarkers (AFP, OPN), but not carcinoma antigens." (PMID 31089160, 2019).
adenocarcinoma (51 papers, 2005 to 2026). A common cancer characterized by the presence of malignant glandular cells. "While AFP-producing adenocarcinoma has multiple underlying molecular mechanisms that correlate with poor prognosis, definitive treatment based on molecular pathways has yet to be defined." (PMID 38817451, 2024). "If AFP+ EC extends to the uterine cervix, clear cytoplasms might cause confusion with gastric-type adenocarcinoma." (PMID 34977100, 2021). "The ROC curve analysis revealed that CA 19-9, CEA, AFP, and CA-125 were excellent predictors of adenocarcinoma, with high sensitivity and specificity, especially when their levels exceeded certain thresholds." (PMID 40332145, 2025). "Laboratory findings revealed significantly elevated levels of CA 19-9, CEA, AFP, and CA-125 in patients with adenocarcinoma." (PMID 40332145, 2025). "Histopathology confirmed adenocarcinoma, and immunohistochemical staining was positive for AFP, establishing a diagnosis of AFPGC with liver metastases (Stage IV)." (PMID 40922714, 2025). "This trial aimed to assess the antitumor activity, safety, and predictive biomarkers of camrelizumab combined with apatinib and chemotherapy in previously untreated patients with AFP-producing G/GEJ (AFP-G/GEJ) adenocarcinoma." (PMID 40082418, 2025). "Despite the different sites of origin, all of them have histomorphologic features of adenocarcinoma and hepatocellular differentiation, often accompanied by large amounts of alpha-fetoprotein (AFP) secretion." (PMID 40740864, 2025). "Considering the distinct feature of AFPGC from typical adenocarcinoma, serum AFP level was expected to be correlated with malignant degree and prognosis." (PMID 38833154, 2024). "The existing AFP-producing adenocarcinomas exhibit unique clinical characteristics, including high malignancy and early metastatic potential, which result in poorer outcomes." (PMID 38817451, 2024). "This underscores the role of HGF/c-Met signaling pathways in the development of AFP-producing adenocarcinomas, providing a clear link between these pathways and the production of AFP." (PMID 38817451, 2024). "Laparoscopic whole-layer cholecystectomy was performed, and histological examination revealed AFP positive poorly differentiated adenocarcinoma with signet ring cells (pT2bN0cM0, pStage IIb, UICC 8th)." (PMID 36402065, 2022). "The prognosis of APA-GI was worse than that of common adenocarcinoma of the GI tract and liver metastasis, and high AFP levels suggest poor prognosis in patients with APA-GI." (PMID 33996549, 2021). "A histopathological examination showed the local production of AFP in moderately to poorly differentiated adenocarcinoma." (PMID 29457212, 2019). "In this study, we demonstrated a patient with poorly differentiated adenocarcinoma with neuroendocrine differentiation in the ascending colon, with an elevated serum AFP." (PMID 26976278, 2016). "The current AFP-GC with PVTT had the elevated level of serum AFP and the poorly differentiated adenocarcinoma cells stained with anti-AFP antibody immunohistochemically." (PMID 25591731, 2015). "In the present study, although HAC concomitant with adenocarcinoma was observed in only one case, AFP was expressed in well- or moderately differentiated adenocarcinomas." (PMID 22482081, 2012). "A prompt and accurate diagnosis of hepatoid adenocarcinoma is important because prognosis is very poor compared with that of both common types of adenocarcinoma and AFP-producing adenocarcinomas." (PMID 17448253, 2007). "HAC does not exhibit any specific imaging features, but elevated serum AFP is more common in HAC than in common adenocarcinomas, which may aid in early detection." (PMID 40740864, 2025). "Pathological results confirmed a diagnosis of AFP-producing poorly differentiated adenocarcinoma." (PMID 38817451, 2024).
adenocarcinoma (continued). "This may support the conclusion that autocrine HGF/c-Met activation may induce the dedifferentiation of standard adenocarcinoma cells into a stem cell state to produce AFP or hepatoid differentiation." (PMID 38817451, 2024). "Notably, clinical investigations of AFP-producing adenocarcinomas have revealed a worrying trend toward high-malignant and metastatic potential, leading to poorer outcomes for patients with these tumors." (PMID 38817451, 2024). "In parallel, the immunohistochemical profile of these adenocarcinomas is characterized by the loss of INI-1 expression, positivity for CK7, CK20 (focal) and CDX2 (focal), as well as positivity for yolk sac markers like glypican-3, alpha fetoprotein and SALL4." (PMID 35326613, 2022). "The immunohistochemical profile of these adenocarcinomas is more complex, and, besides the loss of INI-1 expression, includes positivity for CK7, CK20 (focal) and CDX2 (focal), as well as for yolk sac markers including glypican-3, alpha fetoprotein and SALL4." (PMID 35326613, 2022). "However, abnormally elevated serum AFP is also reported in some kinds of adenocarcinoma, which are called AFP-producing adenocarcinoma (APA)." (PMID 33996549, 2021). "Five (10.4%) non-AFP-producing GC patients had well differentiated adenocarcinoma (WDA)." (PMID 29254216, 2017). "Only one AFP-producing GC patient had well differentiated adenocarcinoma (WDA)." (PMID 29254216, 2017). "The glandular component consisted of a well-to-moderately differentiated adenocarcinoma with clear-cell morphology and enteroblastic features, showing positivity for glypican-3 and SALL4 with focal alpha-fetoprotein expression." (PMID 41969299, 2026). "Cholangiofibrosis, cholangiofibroma, and adenocarcinoma were stained for both CK19−9 and AFP expression, confirming the presence of pre-cancerous and cancerous lesions." (PMID 41144486, 2025). "Laboratory investigations demonstrated that patients with adenocarcinoma had significantly elevated levels of CA 19-9, CEA, AFP, and CA-125, while amylase and total bilirubin levels were notably lower." (PMID 40332145, 2025). "Furthermore, the deeper invasive areas more frequently expressed AFP than the superficial areas, indicating that conventional adenocarcinomas may initially develop in the mucosa, acquire fetal-type traits, invade deeper layers, and subsequently transform into GACED and HAC." (PMID 41041100, 2025). "YST components were immunohistochemically positive for AFP in all cases, but the adenocarcinoma component was generally negative, as confirmed by the current case." (PMID 33956241, 2021). "Accordingly, HAS's clinicopathological entity was extended, involving adenocarcinomas performing histological patterns of similarity to HCC morphologically regardless of AFP expression/production." (PMID 33912455, 2021). "Adenocarcinomas arising from the lung and gastrointestinal tract are almost invariably AFP negative." (PMID 20062599, 2009). "However, approximately 20%–30% of HACs do not produce AFP serum and have normal AFP, but can still be diagnosed as AFP-like adenocarcinoma and called AFP-negative HACs if other major conditions are met." (PMID 40740864, 2025). "- Gland-forming adenocarcinoma without clear cells. - Positive IHC for AFP and/or SALL4." (PMID 34977100, 2021). "Patient 1 (F, 34) presented with mediastinal and retroperitoneal lymph node metastases of a poorly differentiated adenocarcinoma with high plasma levels of CEA, CA125, CA 19-9 and no elevation of β-HCG or AFP." (PMID 18088404, 2007).
infection (49 papers, 2012 to 2025). The state of being infected such as from the introduction of a foreign agent such as serum, vaccine, antigenic substance or organism. "Although our cohort is too small to draw firm conclusions, identifying 1 patient with AFP highlights the importance of further research and monitoring to understand potential complications associated with EV-D68 infection." (PMID 39163309, 2024). "In this study, the multivariate analysis found that AFP was a risk factor for infection after liver resection." (PMID 37046206, 2023). "A line graph was constructed to predict the occurrence of postoperative infections by using the five risk predictors of BMI, preoperative AFP, TBIL, intraoperative blood loss, and bile leakage." (PMID 37046206, 2023). "Multivariate logistic analysis showed that the independent risk factors for infection after hepatectomy were BMI (> 24 kg/m2), preoperative AFP (> 100 μg/L), TBIL, intraoperative blood loss (> 400 ml), and bile leakage." (PMID 37046206, 2023). "A. giganteus AFP at a concentration of 100 μg/mL preincubated with tomato seedlings also prevented the infection of tomato roots by the plant-pathogenic fungus F. oxysporum f.sp." (PMID 30344516, 2018). "Postoperative infection in patients undergoing hepatectomy may be related to risk factors such as BMI, preoperative AFP level, TBIL level, intraoperative blood loss and bile leakage." (PMID 37046206, 2023). "These parameters may suggest that an inflammatory or infection condition occurred in patients with high serum AFP levels, since the AFP status was associated with unfavorable clinical pathologic features." (PMID 35461226, 2022). "Furthermore, serum AFP was postive (the cutoff level of normal serum AFP is ≤20ug/L)) in 72% of HCC patients with the C variant infection, compared to that in 33% of patients with the B variant infection, indicating the elevated AFP in HBV C-type patients (p = 0.052, OR = 4.99)." (PMID 25901726, 2015). "The relation between decreasing AFP levels after treatment for suspected infection was, however, a rare phenomenon." (PMID 38915994, 2024). "The study observed that HBV viral load and alpha-fetoprotein (AFP) levels were higher in HBV/HDV coinfected patients compared to those with HBV mono-infection." (PMID 39599836, 2024). "Studies have shown that AFP can disable the patient’s anti-infection function by inhibiting immune cells." (PMID 37046206, 2023). "BMI, preoperative AFP, TBIL, intraoperative blood loss, and bile leakage are risk factors for postoperative infection." (PMID 37046206, 2023). "Univariate analysis indicated that age, WBC count, Hb, PLT, AST, ALB, TBil, INR, Na, Cr, AFP, HBeAg, HBV DNA, HRS, GB, HE, infection, and PreLD were associated with 90-day transplantation-free survival." (PMID 34222294, 2021). "In the Rag2-Il2rg double-knockout mice transplanted with CD133-negative HepG2 cells, the AFP secretion in the mouse serum after paOAd infection was significantly decreased by blue light irradiation." (PMID 32703933, 2020). "Topical application of the A. giganteus AFP to rice leaves conferred protection M. grisea infection and application to tomato roots decreased infection by F. oxysporum." (PMID 32324832, 2020). "The AFP secretion in the mouse serum after paOAd infection was significantly decreased by blue light irradiation in the Rag2-Il2rg double-knockout mice transplanted with CD133-positive HepG2 cells, while that did not change by Sorafenib treatment." (PMID 32703933, 2020). "Multiple contrasts showed that matings involving AfP− females ended significantly later (p < 0.001) than those involving AfP+ females, irrespectively of the male infection status." (PMID 31797888, 2019). "Two key factors affecting the expression of recombinant human AFP (R-AFP), namely the infectious baculovirus inoculum volume and the culturing time post-infection, were optimized to maximize the yield." (PMID 27913752, 2017).